MUC16 (mucin 16, cell surface associated)
Diseases named in the same sentence as MUC16 in open-access papers (continued):
Sharing a sentence is not in itself a finding about the gene and the disease.
pancreatic cancer (continued). "This integrated approach contributes to a better understanding of how MUC16 and PODXL bind to E-/L-selectins in the presence of hydrodynamic shear, which can lead to improved diagnostic assays and to the prevention of the metastatic spread of pancreatic tumor cells." (PMID 26329844, 2015). "The significantly reduced level of MUC16 observed in miR-200c overexpressing cells, along with the well documented role of miR-200c in multiple stages of cancer progression suggests that MUC16 may have a role in pancreatic cancer cell growth and metastasis." (PMID 24204560, 2013). "In malignancies such as ovarian and pancreatic cancer, MUC16 CTD translocation drives the expression of invasion-related genes, such as NRP2 in pancreatic cancer, promoting disease progression." (PMID 40305342, 2025). "Here, we describe the retained ectodomain of Muc16, Muc16CD, as a novel TAA for targeting by CAR T cell therapy in pancreatic cancer." (PMID 39346763, 2024). "Rafiq and colleagues describe the retained ectodomain of Muc16, Muc16CD, as a novel TAA for targeting by chimeric antigen receptor (CAR) T cell therapy in pancreatic cancer." (PMID 39346763, 2024). "MUC16 upregulates Neuropilin 2 (NRP2) through JAK2 / STAT1 signaling in PDAC and promotes metastasis of pancreatic cancer." (PMID 38758220, 2024). "Several proteins, such as Mucin 16 (MUC16), have been evaluated as FGS targets in pancreatic ductal adenocarcinoma (PDAC), the most common type of pancreatic cancer." (PMID 39456534, 2024). "Zhang reported that the genes MET, MUC16, and KRT7 in the model had high expression levels in pancreatic tumor tissues as validated by RT-qPCR." (PMID 39127853, 2024). "RT-qPCR validated that MET, MUC16, and KRT7 in the model had higher expression levels in pancreatic tumour tissues." (PMID 37815881, 2023). "This work aims to develop fully human antibodies against MUC16 and evaluate them as potential immuno-PET imaging probes for detecting ovarian and pancreatic cancers." (PMID 36559316, 2022). "This Ab elicited antibody-dependent cellular cytotoxicity (ADCC) on pancreatic cancer cells in vitro and blocked the interaction between MSLN and its ligand CA125/MUC16." (PMID 35892707, 2022). "In clinical practice, sialylation-based cancer biomarkers such as pancreatic cancer marker CA19-9 (Sialyl-Lewis a: sLea) and the sialylated mucin biomarkers CA125 (MUC16) and CA15-3 (MUC1 analog) are used to detect ovarian and breast cancers." (PMID 34822576, 2021). "MUC16-Cter also mediated ALDH+ cancer stem cell enrichment which induced tumorigenic, metastatic and drug resistant properties in pancreatic cancer cells." (PMID 29682172, 2018). "We analyzed MUC4, MUC16 and MUC20 expression in pancreatic tumor (T) and paired adjacent non tumoral tissues (ANT) from GSE28735 and GSE16515 (not shown) datasets." (PMID 30236127, 2018). "We observed a positive correlation between MUC16 and c-MYC expression in human pancreatic tumor specimens." (PMID 26046375, 2015). "MUC16 and PODXL have been identified as functional E- and L-selectins ligands that are overexpressed in metastatic pancreatic cancer cells." (PMID 26329844, 2015). "We recently identified sialofucosylated mucin 16 (MUC16) and podocalyxin (PODXL) as the major functional E- and L-selectin ligands expressed on the surface of metastatic pancreatic cancer cells." (PMID 26329844, 2015). "To validate the measurements obtained using immunopurified MUC16 and PODXL, we also tested E-/L-selectin binding to MUC16-expressing (PODXL-knockdown) and PODXL-expressing (MUC16-knockdown) SW1990 pancreatic cancer cells." (PMID 26329844, 2015). "Overall, our result demonstrates that MUC16 mediated c-MYC expression regulates physiology and biosynthetic processes of pancreatic cancer cells." (PMID 26046375, 2015). "Furthermore, single-cell analysis revealed that MET, MUC16, and KRT7 were mainly expressed in the microenvironment of pancreatic cancer cells." (PMID 39127853, 2024).
pancreatic cancer (continued). "Several mucins have shown clinical promise, including MUC1 (also known as CA 15-3 and KL-6, in breast cancer), MUC4 (pancreatic cancer), and MUC5 (gastrointestinal, pancreatic, gastric cancers); however, only one is FDA-approved and in clinical use, MUC16, also known as CA125 in ovarian cancer." (PMID 39767713, 2024). "c-Myc can bind to the promoter of MUC16 and activate muc16 expression transcriptionally, directly or indirectly promote the up-regulation of MUC16 expression and CA125 shed, further mediating the metastasis of pancreatic cancer cells." (PMID 38758220, 2024). "MUC16 promotes epithelial mesenchymal transformation (EMT) and PDAC cell metastasis by upregulating the expression of cytoskeletal proteins Actg2, MYH11, and Pdlim3, and has been found to alter the tumor microenvironment in pancreatic cancer progression." (PMID 38758220, 2024). "DMUC5754A, an ADC that contains a humanized anti-MUC16 with MMAE, was developed and tested in patients with ovarian and pancreatic cancers in Phase I trial, showing that DMUC5754A has anti-tumor activity in MUC16+ patients with an acceptable safety profile (NCT01335958)." (PMID 37509200, 2023). "Indeed, the recently described interaction between MUC16 and FAK is suggested as a mechanism of pancreatic cancer metastasis." (PMID 34681277, 2021). "We reported that MUC16 and mesothelin were overexpressed only in infiltrating pancreatic cancer cells but not in PanIN-3 cells or normal pancreatic tissues." (PMID 30140382, 2018). "Along these lines, combination treatment of pancreatic cancer cells with absent (or nearly undetectable) MUC16 expression did not result in a differential killing profile between the two TRAIL drugs." (PMID 27120790, 2016). "Overall, our results suggest that MUC16 plays an important role in PDAC metastasis; therefore, it may represent a novel target in pancreatic cancer." (PMID 27382435, 2016). "Recently, it has been shown that MUC16 expression is significantly increased in pancreatic cancer, but its role in the pathogenesis is not well understood." (PMID 26046375, 2015). "MUC16 is a heavily glycosylated transmembrane protein, which is expressed in epithelial ovarian cancer and metastatic pancreatic cancer cells but not in normal pancreatic cells." (PMID 26329844, 2015). "Since the pancreatic cancer cells used in this study have high, albeit heterogeneous, MUC16 expression, in addition to heterogeneous MUC1 expression, we wanted to investigate the immune shielding effect of MUC1 and MUC16 in regard to ADCC." (PMID 24039759, 2013). "Pancreatic cancer cell lines S2.028 and T3M-4 transfected with miR-200c showed a 4.18 and 8.50 fold down regulation of MUC4 mRNA, and 4.68 and 4.82 fold down regulation of MUC16 mRNA compared to mock-transfected cells, respectively." (PMID 24204560, 2013). "The role of MUC16 in metastasis involves regulating the expression levels of E-cadherin and vimentin, inhibiting the release of apoptotic ligands from breast cancer cells, promoting the nuclear translocation of JAK2 in pancreatic cancer cells, and modulating immune evasion." (PMID 40699805, 2025). "The unique structural features of Muc16 and mesothelin proteins represent critical biology that may contribute to the success or failure of existing CAR T therapies targeting these antigens in pancreatic cancer." (PMID 39346763, 2024). "Unlike MUC16 knockdown reduction, which significantly reduced colony formation and migration, ectopic overexpression of MUC16-Cter showed a significant increase in colony formation and movement in MiaPaCa2 pancreatic cancer cells." (PMID 38758220, 2024). "Overexpression of C1GalT in pancreatic cancer reduced the appearance of the TF precursor structure Tn on integrin-αV and -α5 whereas knockdown of C1GalT1 in T3M4 PDAC cells increased Tn occurrence on mucin protein MUC16 and increased phosphorylation of integrin-α4." (PMID 34944925, 2021).
pancreatic cancer (continued). "The MUC16 C-terminal subunit promotes nuclear translocation of JAK2, the expression of which is increased and activated in the lungs and pulmonary arteries of patients with IPF; the nuclear co-localization of these substances imparts tumorigenic and metastatic processes in pancreatic cancer cells." (PMID 31514468, 2019). "Tunicamycin or MG132 treatment ofMiaPaCa-2 and T3M4 pancreatic cancer cells stably transfected with CMV9-F114HAresulted significant abrogation of higher molecular weight forms and increasedaccumulation of MUC16-Cter, respectively suggesting MUC16-Cter undergoes N-glycosylation and ubiquitylation." (PMID 26044153, 2015). "Similar activity profiles were obtained for all three drugs on other cell types known to be largely devoid of MUC16-expression, again highlighting the similarity between Meso64-TR3 and non-targeted TR3 relative to Meso-TR3 (BxPC3 pancreatic cancer)." (PMID 27120790, 2016).
breast carcinoma (84 papers, 2009 to 2025). "Muc16 expression is demonstrated to be associated with the development of different cancer types including pancreatic and breast cancers." (PMID 35116056, 2021). "MUC16 mutations were among the most frequent, both in ovarian and breast cancer samples in the present study." (PMID 34944094, 2021). "For example, BRCA mutations are associated with unfavorable prognosis in breast cancer patients; in addition, a higher MUC16 gene mutation rate indicates a more favorable prognosis in patients with stomach adenocarcinomas." (PMID 34552618, 2021). "PIK3CA and MUC16 mutation was frequently observed in high AR expressing breast cancer (p =.017and .013, respectively)." (PMID 28060723, 2017). "Studies performed to investigate the functional role of MUC16 in ovarian, and breast cancer has implicated MUC16 to play an important role in cell proliferation, resisting apoptosis and immune evasion." (PMID 27382435, 2016). "MUC16 is also overexpressed in many malignancies, including ovarian, pancreatic and breast cancers and its overexpression is associated with poor prognosis." (PMID 24722639, 2014). "It was recently shown that MUC16 silencing in breast cancer cells is associated with up-regulation of TRAIL-R1 (DR4) and pro-apoptotic molecules Bid and Bax, and down-regulation of Bcl-2." (PMID 24690311, 2014). "Our gene ontology studies indicated that MUC16 was found to be linked to RNA biosynthesis, cell death, and cell migration pathways, suggesting that MUC16 may mediate these pathways during breast cancer progression." (PMID 36918912, 2023). "Interestingly, consistent with our findings Muc16 overexpression in epithelial breast cancer tissues is demonstrated to be positively associated with the stage of the disease." (PMID 35116056, 2021). "However, association between the stage of breast cancer and elevated Muc16 expression as well as incidence of higher stages of the disease in younger patients support our findings." (PMID 35116056, 2021). "MUC16 is overexpressed in breast cancer tumors and associated with disease stages." (PMID 34207556, 2021). "Both of these approaches identified driver gene mutations in breast cancer-associated genes, such as MUC16, NF1, and BRCA2, suggesting that using different predictive computational tools improves the sensitivity and specificity in identifying cancer somatic mutations." (PMID 32650480, 2020). "Another dataset (GDC data portal) also shows the MUC16 expression is significantly upregulated in various metastases (individual metastases not available) (N = 40) as compared to primary breast tumors (N = 1334), indicating that the MUC16/HuR axis is associated with breast cancer metastasis." (PMID 36918912, 2023). "Cancer antigen 125 (CA125) for ovarian cancer as well as cancer antigen 15–3 (CA15-3) and cancer antigen 27–29 (CA27-29) for breast cancer are based on mucin proteins mucin-16 (MUC16) and mucin-1 (MUC1), respectively." (PMID 38515194, 2024). "MUC16 has been reported to take part in breast cancer progression and metastasis when overexpressed due to its influence on cell cycle and survival through the JAK2/STAT3 pathway." (PMID 39723380, 2024). "MUC1 and MUC16, as key biomarkers in gynecological tumors, particularly ovarian and breast cancers, have attracted significant attention for their roles and potential in tumor immunotherapy." (PMID 38361923, 2024). "CA125 is a product of the MUC16 gene and is an important regulator of multiple pathways involved in the cell survival of breast cancer and ovarian cancer." (PMID 38794187, 2024). "The impact of MUC1 and MUC16 on the progression of breast cancer has been extensively studied and confirmed." (PMID 38361923, 2024).
breast carcinoma (continued). "To understand the potential role of MUC16 in response to chemotherapy in breast cancer patients, we analyzed the expression of MUC16 in the TCGA-BRCA cohort in the therapy naive patients and those treated with any chemotherapeutic regimen." (PMID 36918912, 2023). "Since breast cancer is highly heterogeneous at the molecular level, we analyzed the MUC16 expression in the different molecular subtypes of breast cancer." (PMID 36918912, 2023). "Like MUC16, patients with high HuR protein expression (Q15717) had a significantly worse overall survival compared to those with low HuR expression breast cancer patients (P = 0.055)." (PMID 36918912, 2023). "To assess the clinical impact of MUC16 in breast cancer, we performed immunohistochemistry (IHC) in a breast cancer TMA, which consisted of moderately differentiated (N = 25) and poorly differentiated (N = 36) tumors." (PMID 36918912, 2023). "To investigate the clinical impact of MUC16 on breast cancer metastasis, we analyzed MUC16 expression in publicly available patient datasets of metastatic breast cancer." (PMID 36918912, 2023). "Further, MUC16 was significantly overexpressed in lung tropic cells, and patient data also revealed that MUC16 is elevated in breast cancer lung cancer metastatic tissues, suggesting that MUC16 is involved in breast cancer lung metastasis." (PMID 36918912, 2023). "Increased MUC16 expression in breast cancer also promotes cell cycle progression (G2-M) and cell survival via JAK2/STAT3 signaling pathway." (PMID 36918912, 2023). "The role of MUC16 in promoting tumorigenicity has been widely demonstrated in ovarian and breast cancers, as has been recently extended to PDAC." (PMID 35628269, 2022). "In breast cancer, MUC16 plays a dual role in cell proliferation through interacting with JAK2, and inhibits the cellular apoptosis by TRAIL downregulation." (PMID 34150633, 2021). "In our study, the neoantigens shared by most breast cancer patients (23 out of 729) were MUC16/CA125." (PMID 34207556, 2021). "Several studies have reported on the role of MUC16 in different types of cancers including breast cancer." (PMID 32731431, 2020). "It has been shown that TNF-α and/or IFN-γ stimulated MUC16 mRNA levels in a dose dependent manner in ER positive breast cancer cells." (PMID 29202842, 2017). "Recently, we have shown that MUC16 knockdown in breast cancer cells resulted in the rapid transition from G1/S phase and subsequent arrest in the G2/M phase." (PMID 27382435, 2016). "Further, it has also been shown that knock down of MUC16 in breast cancer cells resulted in a decrease of Cyclin B1 and activation of Aurora Kinase A levels." (PMID 27382435, 2016). "It turned out that, the protein levels of β-catenin, Snail, Axin 2 and Cyclin D1 in the carcinoma tissue (C) were elevated along with MUC16 in the number 1 and number 2 breast cancer samples, compared with the counterparts of normal tissue (N)." (PMID 27167110, 2016). "Mouse mammary cancer cells with intact Jak2 (Jak2+/+) resulted in up regulation of Lmo2 and Nanog in MUC16-Cter dependent manner and this dependence was abrogated in cells genetically deleted for Jak2 (Jak2−/−)." (PMID 25691062, 2015). "Similarly to MUC1 discussed in breast cancer, MUC16 has also been identified to bind to Siglec-9, attenuating T and NK cell functions to help the survival of cancer cells." (PMID 40699805, 2025).